RBP4 (retinol binding protein 4)
Diseases named in the same sentence as RBP4 in open-access papers (continued):
Sharing a sentence is not in itself a finding about the gene and the disease.
ovarian carcinoma (continued). "The overexpression of RBP4 in ovarian cancer cells promotes cancer cell migration and proliferation." (PMID 29642915, 2018). "In conclusion, this study described the function of RBP4 in driving ovarian cancer cell migration and proliferation." (PMID 29642915, 2018). "The results showed that ovarian cancer cells with RBP4 overexpression grows faster than control cells, while the RBP4 knockdown inhibited cell proliferation." (PMID 29642915, 2018). "The mRNA level of RBP4, as revealed by qRT-PCR, was twofold higher in ovarian cancer tissues comparing to the benign ovarian tissues." (PMID 29642915, 2018). "We further investigated which signaling pathways are utilized by RBP4 to activate ovarian cancer cell migration." (PMID 29642915, 2018). "Here we further explored the consequence of RBP4 upregulation in ovarian cancer cells and its molecular mechanism." (PMID 29642915, 2018). "Collectively, these results indicated that RBP4 promotes migration and proliferation of ovarian cancer cells." (PMID 29642915, 2018). "Our data showed that RBP4 was up-regulated in ovarian cancer cells and overexpression of RBP4 promoted cancer cell migration." (PMID 29642915, 2018). "Western blot results showed that the RBP4 protein was upregulated by nearly 4-fold in ovarian cancer tissues comparing to the benign ovarian tissues." (PMID 29642915, 2018). "Our results indicated that RBP4 can drive ovarian cancer cell migration and proliferation via RhoA/Rock1 and ERK pathway." (PMID 29642915, 2018). "Our results show that RBP4 is overexpressed in ovarian cancer cells to the same extent as in adipose tissues." (PMID 29642915, 2018). "We proved that high level of RBP4 can stimulate migration and proliferation of ovarian cancer cells." (PMID 29642915, 2018). "We observed that knockdown of RBP4 can greatly suppress ovarian cancer cell migration and proliferation." (PMID 29642915, 2018). "We used ovarian cancer cell line A2780 and SKOV3 to test the effects of RBP4 expression on ovarian cancer." (PMID 29642915, 2018). "RBP4, a tumor suppressor in ovarian cancer, is negatively regulated by NFIL3 and has lower gene expression value in NG group." (PMID 27586240, 2016). "The plasma concentrations of RBP4 ranging from 76.91 to 120.08 ng/mL with the mean value 89.13 ± 1.67 ng/mL in ovarian cancer patients are significantly higher than those in healthy individuals (10.85 ± 2.38 ng/mL)." (PMID 25250314, 2014). "Given the current progress regarding combinatory multiple ovarian cancer markers, we are investigating the potential to use RBP4 as an adjunct markers in combination with CA125 for ovarian cancer diagnosis." (PMID 25250314, 2014). "ELISA was employed to measure plasma concentrations of RBP4 in 80 samples from ovarian cancer patients, healthy individuals, myoma patients, and patients with benign ovarian tumor, respectively." (PMID 25250314, 2014). "Results were further confirmed with immunohistochemistry, demonstrating that RBP4 expression levels in normal ovarian tissue were lower than those in ovarian cancer tissues." (PMID 25250314, 2014). "In addition, elevated RBP4 expression has been mentioned in ovarian cancer, breast cancer, and pancreatic cancer." (PMID 41007818, 2025). "Moreover, RhoA/Rock1 pathway activation and upregulation of CyclinD1 were involved in RBP4-induced ovarian cancer cell migration." (PMID 38913193, 2024). "RBP4 was overexpressed in ovarian cancer cells, similar to adipose tissues." (PMID 38913193, 2024). "Additionally, RBP4, identified as a serum marker for ovarian cancer, directly induces cancer progression of ovarian cancer cells by increasing the expression of the cancer metastasis factors MM2 and MM9 through the RhoA/Rock1 pathway." (PMID 34068244, 2021).
ovarian carcinoma (continued). "Recently, RBP4 has been detected in serum, plasma, liver, adipose, and kidney samples, and dysregulation of RBP4 has been associated with a variety of diseases, including ovarian diseases, such as PCOS and ovarian cancer in humans and ovarian cysts in swine." (PMID 34068244, 2021). "RBP4 is an adipokine that has been reported to drive the migration of ovarian cancer cells." (PMID 33335850, 2020). "We first detected the RBP4 expression levels in ovarian cancer tissues." (PMID 29642915, 2018). "Here, we established a direct molecular linkage between adipokine RBP4 and ovarian cancer." (PMID 29642915, 2018). "It suggests that RBP4 act as a oncogene in ovarian cancer cells." (PMID 29642915, 2018). "Moreover, RBP4 highly expressed in ovarian cancer cells and high level of RBP4 had been documented in ovarian patient’s serum samples." (PMID 29642915, 2018). "The extent of RBP4 overexpression was comparable in ovarian cancer cells and in adipose tissues." (PMID 29642915, 2018). "We have shown that RBP4 overexpression can greatly stimulate ovarian cancer cell migration." (PMID 29642915, 2018). "Previously, we have identified RBP4 as a serum marker for ovarian cancer." (PMID 29642915, 2018). "Recently, we found that RBP4 level is highly upregulated in ovarian cancer serum samples." (PMID 29642915, 2018). "Though some studies showed that serum RBP4 was upregulated in some cancers such as ovarian and pancreatic cancers, many other studies found significantly decreased levels of serum RBP4 in cancers such as ovarian cancer, HCC, head and neck cancer, and breast cancer." (PMID 29190912, 2017). "Retinol binding protein 4 (RBP4) is highly upregulated in the ovarian cancer serum samples." (PMID 25250314, 2014). "In addition, RBP4 was shown to drive ovarian cancer cell migration; pretreatment plasma D-dimer levels were associated with chemoresistance and poor disease outcome; and low expression of kallistatin was associated with unfavorable prognosis, platinum resistance, and relapse." (PMID 32899818, 2020). "We tested whether the RBP4 effect on ovarian cancer cells is RA dependent." (PMID 29642915, 2018). "RBP4 is highly related to ovarian diseases, such as PCOS, ovarian cancer in humans, and ovarian cysts in swine, which may be caused by endocrine disorders." (PMID 31412686, 2019). "STRA6 expressed in the ovarian cancer cell lines, although its level was not affected by RBP4." (PMID 29642915, 2018).
vitamin A deficiency (21 papers, 2012 to 2025). Deficiency of vitamin A due to malnutrition, malabsorption, or dietary lack. "Ferritin, RBP4, and sTfR were categorized as; ferritin < 15 μg/L to be iron storage deficiency, RBP4 < 0.7 μmol/L, functional vitamin A deficiency and sTfR > 8.3 mg/L as functional iron deficiency." (PMID 39728830, 2024). "RBP4 has been proposed as an indirect measure of nutrition and vitamin A deficiency and vitamin A has been found to contribute to disease severity in its absence." (PMID 37976323, 2023). "It therefore seems unlikely that partial pharmacological reduction of serum RBP4 by RBP4 antagonists to precipitate symptoms of systemic vitamin A deficiency in individuals who maintain a standard vitamin A- and β-carotene-sufficient diet." (PMID 31978148, 2020). "Overall, using the well-studied Rbp4−/− mouse model of vitamin A deficiency, we found that BCO2 deficiency exacerbated embryonic retinol deficiency and the associated malformations." (PMID 29892071, 2018). "Additionally, individuals with vitamin A deficiency tend to have lower levels of both retinol and its transport protein, retinol-binding protein 4, in their cerebrospinal fluid." (PMID 40143179, 2025). "However, after categorizing RBP4 levels, the cut off value RBP4 < 0.7 μmol/L for functional vitamin A deficiency, six children diagnosed with malaria had functional vitamin A deficiency." (PMID 39728830, 2024). "Consistently, vitamin A-deficiency in rats decreases serum-RBP4 levels while inducing its accumulation in liver and adding retinol to retinol-depleted hepatocytes increases RBP4 secretion." (PMID 33790810, 2021). "Additionally, vitamin A deficiency reduces serum RBP4 levels, and, hence, it is essential to evaluate not only the metabolism of vitamin A but also its dietary intake when assessing RBP4 concentrations." (PMID 32718041, 2020). "The insufficient levels of RBP4 observed by proteomics might therefore contribute to vitamin A deficiency." (PMID 30824564, 2019). "RBP4 has been identified as a proxy for vitamin A deficiency which is well known for its association with increased disease severity and reduced immune response and could potentially explain the negative correlation with immune responses observed against both oral and parenteral vaccines." (PMID 37976323, 2023). "In this group of patients, decreased RBP4 levels could be causative for vitamin A deficiency." (PMID 35631143, 2022). "Even though a lesser extent of RBP4 reduction may be required for clinical efficacy in dry AMD, this significant RBP4 lowering raises a concern on whether a highly potent RBP4 antagonist may induce clinically significant adverse effects due to systemic vitamin A deficiency." (PMID 31978148, 2020). "Since the eye is the human organ most sensitive to vitamin A deficiency during development and in adulthood, we used retinal phenotypes and quantified ocular retinoid content, as functional readouts to study the effects of loss of the proposed RBP4-ROL binding domain in Rbpr2, for vision." (PMID 32365517, 2020). "Retinol-binding protein 4 (RBP4) is not essential for spermatogenesis; however, it plays a vital role in protecting the testes from the effects of dietary vitamin A deficiency." (PMID 40331949, 2025). "A possible explanation for the decrease of RBP-4 in IBD patients with 25(OH)D deficiency in our study could be the coincidence of vitamin D and vitamin A deficiency as another fat-soluble vitamin." (PMID 38961351, 2024). "Patients without RBP4 in their blood due to compound heterozygous missense mutations in RBP4 display no clinical symptoms of systemic vitamin A deficiency." (PMID 31978148, 2020). "Specifically, the lack of BCO2 on the vitamin A deficiency-susceptible Rbp4−/− background reduced embryonic retinol levels, regardless of the vitamin A content of the diet." (PMID 29892071, 2018).
vitamin A deficiency (continued). "Further, we have observed an increased incidence of unsuccessful pregnancies upon β-carotene treatment of other models of embryonic vitamin A deficiency with intact carotenoid cleavage enzymes, including mice lacking both RBP4 and LRAT (Lrat−/−Rbp4−/−36; 50% unsuccessful pregnancies)." (PMID 29892071, 2018). "Serum retinol and RBP4 concentrations were significantly lower in HCV subjects compared to controls, although no HCV subjects met the standard serum criteria for vitamin A deficiency (<200 ng/mL)." (PMID 26927700, 2016).
Glucose intolerance (20 papers, 2009 to 2025). Glucose intolerance (GI) can be defined as dysglycemia that comprises both prediabetes and diabetes. "RBP4 is associated with ocular diseases, impaired vision, dysregulation of lipid homeostasis, metabolic disorders, glucose intolerance, and cardiovascular disorders." (PMID 38673873, 2024).
Stroke (19 papers, 2015 to 2025). Sudden impairment of blood flow to a part of the brain due to occlusion or rupture of an artery to the brain. "Peripheral blood samples from 265 stroke patients and 50 healthy controls (HCs) were collected at enrollment for serum RBP4 (by enzyme-linked immunosorbent assay) and Th17 and Treg cells (by flow cytometry) determination." (PMID 37808505, 2023). "For predicting onset and progression of neurological disease, RBP4 has been suggested as a biomarker relevant to stroke and brain injury risk." (PMID 37674727, 2023). "Serum RBP4 is positively associated with a Th17/Treg cell imbalance and, more importantly, it is indicative of cognitive function decline within 3 years in stroke patients." (PMID 37808505, 2023). "In stroke patients, serum RBP4 was positively associated with Th17 cells (p < 0.001), and the Th17/Treg ratio (p < 0.001) and negatively associated with Treg cells (p = 0.003)." (PMID 37808505, 2023). "Retinol-binding protein 4 (RBP4) promotes atherosclerotic progression and neuronal loss, whereas its association with cognitive impairment in stroke is unclear." (PMID 37808505, 2023). "Further studies should be carried out with respect to what was the cause of the increased serum levels of RBP4 and the role in the pathology of the stroke outcomes." (PMID 30038059, 2018). "At last, a major limitation of the present investigation was the cross-sectional design, which prevented us from inferring cause–effect relationship of RBP4 with stroke outcomes." (PMID 30038059, 2018). "As a result, the present study focused on the correlation of RBP4 with Th17 cells, which revealed that serum RBP4 was positively associated with Th17 cells and the Th17/Treg ratio and negatively associated with Treg cells in stroke patients." (PMID 37808505, 2023). "Therefore, elevated serum RBP4 was associated with the occurrence of hyperlipidemia in stroke patients." (PMID 37808505, 2023). "Therefore, this prospective study aimed to investigate the association of serum RBP4 with Th17/Treg balance, disease characteristics, and the long-term progression of cognitive impairment in stroke patients." (PMID 37808505, 2023). "Meanwhile, serum RBP4 had a satisfactory value to distinguish stroke patients from HCs, with an area under the curve (AUC) value of 0.815 (95% confidence interval: 0.750–0.879)." (PMID 37808505, 2023). "As a result, serum RBP4 was negatively associated with baseline and 1-, 2-, and 3-year MMSE scores but positively associated with 1-, 2-, and 3-year MMSE score decline in stroke patients." (PMID 37808505, 2023). "In summary, elevated serum RBP4 is associated with Th17/Treg imbalance and aggravated 1-, 2-, and 3-year MMSE score decline, with the potential to reflect cognitive impairment in stroke patients to some extent." (PMID 37808505, 2023). "Apart from the positive relationship between serum RBP4 and Th17/Treg imbalance, the current study also found that increased serum RBP4 was associated with hyperlipidemia, CVD, and recurrent stroke in stroke patients." (PMID 37808505, 2023). "This study first demonstrated the positive correlation between serum RBP4 and Th17 cells and 3-year cognitive impairment in stroke patients." (PMID 37808505, 2023). "Serum RBP4 was elevated in stroke patients compared to HCs (p < 0.001), with a good ability to differentiate stroke patients from HCs (area under the curve: 0.815)." (PMID 37808505, 2023). "Serum RBP4 was elevated in stroke patients compared to HCs [median interquartile range (IQR): 33.0 (26.0–45.6) μg/mL vs. 19.1 (14.6–24.5) μg/mL, p < 0.001]." (PMID 37808505, 2023). "Increased serum RBP4 was associated with hyperlipidemia (p = 0.017), CVD (p = 0.006), and recurrent stroke (p = 0.011)." (PMID 37808505, 2023). "A study on acute ischemic stroke found a significantly higher serum RBP4 level in stroke patients than in normal controls (28.9 versus 23.7 μg/mL)." (PMID 37510153, 2023).
Stroke (continued). "At the same time, AIS patients with high serum RBP4 level had mild stroke severity, good short-term prognosis, and improved treatment effect, which improved patients' quality of life." (PMID 36043144, 2022). "Therefore, we speculated that serum RBP4 might be associated with stroke risk and prognosis." (PMID 30038059, 2018). "The plasmatic retinol-binding protein 4 (RBP4) was picked up on a big screen that aimed to identify new biomarkers to differentiate the stroke subtypes." (PMID 29490898, 2018). "Serum levels of RBP4 were assayed and severity of stroke was evaluated with the National Institutes of Health Stroke Scale (NIHSS) score on admission." (PMID 30038059, 2018). "The serum levels of RBP4 were significantly higher in stroke patients as compared with normal cases (27.3 (IQR: 18.6–36.4) μg/ml compared with 17.6 (IQR: 11.8–23.5) μg/ml; P<0.001)." (PMID 30038059, 2018). "Consequently, early and timely interventions and physical rehabilitation are more necessary in stroke patients with high serum RBP4." (PMID 37808505, 2023). "Correlation of RBP4 with characteristics of stroke patients." (PMID 37808505, 2023). "Besides, the ROC curve showed the ability of serum RBP4 to estimate the cognitive decline in stroke patients, with an AUC value of 0.632." (PMID 37808505, 2023). "More importantly, serum RBP4 was negatively correlated with 1-, 2-, and 3-year MMSE scores (all p < 0.001) and positively associated with 1-year (p = 0.013), 2-year (p = 0.007), and 3-year (p = 0.001) MMSE score declines in stroke patients." (PMID 37808505, 2023). "Furthermore, increased serum RBP4 was associated with a lower MMSE score (p < 0.001) and a lower incidence of cognition impairment (p = 0.005) at enrollment in stroke patients, as were Th17 cells and the Th17/Treg cell ratio (all p < 0.050)." (PMID 37808505, 2023). "This study has shown that serum RBP4 was negatively associated with baseline (at enrollment) and 1-, 2-, and 3-year MMSE scores but positively associated with 1-, 2-, and 3-year MMSE score decline in stroke patients." (PMID 37808505, 2023). "Thus, early and timely interventions and physical rehabilitation are more necessary in stroke patients with high serum RBP4." (PMID 37808505, 2023). "Conceivably, RBP4 is speculated to possess a predictive role for cognitive impairment in stroke patients." (PMID 37808505, 2023). "Serum levels of RBP4 increased with increasing severity of stroke as defined by the NIHSS score." (PMID 30038059, 2018). "We also examined the relationship between serum RBP4 levels and stroke subtypes." (PMID 30038059, 2018). "Thus, serum RBP4 was positively associated with Th17 cells and the Th17/Treg ratio but showed a weak negative association with Treg cells in stroke patients." (PMID 37808505, 2023). "Consequently, it is speculated that RBP4 may also regulate the Th17 ratio, which plays an essential role in stroke progression." (PMID 37808505, 2023). "The following pathways could be considered for the role of RBP4 in the stroke." (PMID 30038059, 2018). "For RBP4 values > 61 mcg/mL and GFAP < 0.07 ng/mL, the specificity in discerning between the two subtypes of Stroke is 100%." (PMID 37511304, 2023). "Thus, elevated RBP4 may have a role in stroke prognosis, and its mechanisms need to be elucidated." (PMID 30038059, 2018). "In contrast, the levels of transthyretin (TTR), apolipoprotein C-II (ApoC2), and retinol-binding protein 4 (RBP4) were lower in patients with stroke and AF compared to those without AF." (PMID 38886511, 2024). "A1AG1, CRP, and LBP were upregulated, while TTR, ApoC2, and RBP4 were downregulated in patients with stroke and AF, compared to patients with stroke without AF." (PMID 38886511, 2024). "Elevated levels of RBP4 have been found among women who had a stroke compared to those who did not have a stroke during the discovery phase based on data from the Women’s Health Initiative." (PMID 36699006, 2022).
Stroke (continued). "Furthermore, secretion of adipokines, including omentin-1, retinol-binding protein 4 (RBP4), fatty acid–binding protein 4 (FABP4) was altered in adipose tissue dysfunction and might play role in the prognosis of stroke." (PMID 32771014, 2020).